STAT3 (signal transducer and activator of transcription 3)
Diseases named in the same sentence as STAT3 in open-access papers (continued):
Sharing a sentence is not in itself a finding about the gene and the disease.
tumor (continued). "The role of TGF-β was demonstrated by antibody blocking experiments in which anti-IL-10 plus anti-TGF-β antibodies could reproduce the effects of STAT3 targeting of H22 cells in in vivo tumor growth experiments." (PMID 27148255, 2016). "Furthermore, in tumor cell lines, STAT3 promoted proliferation and cell survival, while STAT1 was antiproliferative and pro‐apoptotic." (PMID 26931423, 2016). "Our findings also showed that levels of phosphorylated ERK and STAT3 increased in proliferative tumor cells suggesting that inhibition of PI3K/AKT pathway activates MAPK and JAK/STA3 survival signaling that could eventually lead to therapeutic resistance." (PMID 26910118, 2016). "In the present study, however, copy number gains of JAK2 were not positively associated with expression of p-STAT3 in tumor cells." (PMID 27050074, 2016). "Direct or indirect Stat3 pathway activation by IL-17A promotes the proliferation and progression of various tumors, whereas IL-17A-mediated adaptive and innate immune responses exert anti-tumor effects." (PMID 27462789, 2016). "Finally, we identified that IL-6/P38 MAPK and IL6/STAT3 pathways play critical roles in DR6-related tumor angiogenesis." (PMID 26950598, 2016). "The miR-197/CKS1B/STAT3 axis can drive tumor PD-L1 expression as a biomarker of this cascade, and miR-197 replacement therapy may be a potential treatment strategy for chemoresistant NSCLC." (PMID 26919108, 2016). "IL-6 suppression or JAK/STAT3 pathway inhibition reduced CTC seeding in primary tumours." (PMID 26623559, 2016). "Constitutive STAT3 phosphorylation in tumor cells is usually driven by the overproduction of key cytokines and growth factors, such as IL-6, IL-10, EGF, HGF, Her2/Neu, and VEGF, or their receptors, as well as aberrantly activated cytoplasmic kinases, such as Src, among others." (PMID 27148255, 2016). "Interestingly, STAT3 signaling was unevenly inactivated in the tumor tissues, and regions showing STAT3 inhibition exhibited extensive cell death." (PMID 27716625, 2016). "The present results suggest that STAT1 and STAT3 may affect disease outcome through direct impact on tumour cells, counteracting aggressive tumour features, as well as interaction with the surrounding microenvironment." (PMID 27769057, 2016). "Nevertheless, it must be mentioned that MDSCs present at the tumor site might indeed show resistance toward STAT3 inhibition." (PMID 27827921, 2016). "Furthermore, expression of dominant-negative STAT3 is sufficient to inhibit cell migration, invasion, and tumor formation in nude mice." (PMID 27756245, 2016). "Importantly, inhibition of these STAT3 targets suppressed tumor growth and metastasis in a variety of cancers including pancreatic, head and neck and colorectal." (PMID 26742077, 2016). "We also investigated how the BRG1's regulation of the tumor-induced lymphangiogenesis depended on STAT3 and VEGFC, which is a mechanism that could be blocked by STAT3 inhibitor or the VEGFC antibody." (PMID 27145366, 2016). "Recently, accumulating studies have demonstrated STAT3-targeted therapy could effectively restrain tumor development in various solid tumors." (PMID 26959884, 2016). "Inhibition of STAT3 significantly enhanced the drug-induced apoptosis of the tumor cells." (PMID 27340780, 2016). "Being different from normal cells, which phosphorylate STAT under stringent control, STAT3 is continuously phosphorylated in several neoplastic diseases via the overproduction of agonists, such as specific cytokines, namely, IL-6, and their respective cytokine receptors." (PMID 27190500, 2016). "Thus, we conclude that a higher ratio of STAT1/STAT3 expression was accompanied by better prognosis and slower xenograft growth, with smaller tumor size." (PMID 27191495, 2016). "This association may be attributed to the overexpression of several growth factors, MMP2 and VEGF, which are induced by Stat3 activation and subsequently promote tumor invasion and angiogenesis." (PMID 27460364, 2016).
tumor (continued). "Although STAT3 is widely considered to be an oncogene, emerging evidence suggests STAT3 may also suppress tumor growth." (PMID 27078846, 2016). "DR6-deficient suppression of tumor angiogenesis is regulated by IL-6 via NF-κB, P38/MAPK and STAT3." (PMID 26950598, 2016). "These two effects might play a independent and synergistical role in the anti-tumor process of IL-37b.However, is there a crosstalk between STAT3 and pSmad3L?" (PMID 27835881, 2016). "This assay thus demonstrated that SC09 delayed MM tumor growth by targeting STAT3 signaling." (PMID 27705908, 2016). "Given the previous observation that tumors with MMTV-Cre directed excision could select against tumor progenitor cells with Cre expression, we examined tumors from Myc Stat3 CKO mice for excision." (PMID 27589562, 2016). "This local increase of cytokines surrounding tumor cells might collaborate in tumorigenesis by activating the NFkB and/or STAT3 pathways." (PMID 27901106, 2016). "STAT3 activation has been found to be responsible for tumor immune escape." (PMID 26900950, 2016). "STAT3 controls numerous indirect effects on NKs through cytokine secretion by tumor cells, developmental regulation of DCs, as well as chemokine and cytokine production by DCs, macrophages, and MDSCs, all of which exert feedback controls on NK cell migration, activation, and lytic activity." (PMID 27148255, 2016). "Thus, our results suggest that 4-MD inhibits the JAK2/STAT3 signaling, which in turn leads to suppression of tumor growth in vitro and in vivo." (PMID 26755649, 2016). "LS174T xenografts displayed a significant reduction in tumor growth upon STAT3 knockdown." (PMID 27191495, 2016). "Moreover, NZ restored the doxorubicin-induced immunogenic cell death and reversed the tumor-induced immunosuppression due to the production of kynurenine, by inhibiting the STAT3/indoleamine 2,3 dioxygenase axis." (PMID 26980746, 2016). "In another study, the receptor tyrosine kinase inhibitor sunitinib was shown to inhibit Stat3, leading to down regulation of angiogenic gene expression as well as the reduction of MDSCs and regulatory T cells, resulting in tumor cell apoptosis and growth arrest in renal cell carcinoma." (PMID 27655678, 2016). "Importantly, 4-MD reduced colony formation in soft agar and inhibited tumor growth in mice xenograft model in association with the reduced expression of PCNA, Ki67, p-STAT3, and Survivin." (PMID 26755649, 2016). "KSHV was found to increase STAT3 and NFκB levels in a tumor maintenance model in mice." (PMID 27458446, 2016). "Furthermore, engagement of VEGF/VEGFR2 signaling directly in CRC cells leads to STAT3 phosphorylation and promotes tumor development." (PMID 27148488, 2016). "Taken together, these results suggest that EBI3 may mediate a bidirectional reciprocal-regulation STAT3 signaling pathway to assist the tumor escape immune surveillance in CRC." (PMID 27247488, 2016). "In this setting, increased STAT3 phosphorylation could also be observed in the Δhep non-tumour tissue, likely a result of the inflammatory reaction in these organs." (PMID 28000790, 2016). "To determine the effect of C188-9 treatment on STAT3 gene targets, especially pro-oncogenic genes, we isolated total RNA from tumor xenografts harvested from mice treated with vehicle (n=5), C188 (n=4), or C188-9 (n=6) and used it for RNA sequencing and analysis." (PMID 27027445, 2016). "Moreover, 14,15-EET can cooperate with G-CSF/IL-6 to more efficiently induce the enhanced and sustained activation of STAT3, thus inducing the conversion of neutrophil function from tumor-suppressing to tumor-promoting." (PMID 27270316, 2016). "Besides, specific STAT3 ablation in IECs interfered with tumor formation and tumor growth in the AOM-DSS model." (PMID 27582544, 2016).
tumor (continued). "Tumor and immune cells can communicate through nuclear factor kappa-light-chain-enhancer of activated B cells (NF-κB) and signal transducer and activator of transcription 3 (STAT3)-dependent cytokine production." (PMID 27784305, 2016). "These pro-tumorigenic cytokines include interleukin (IL)-6, IL-11, IL-21 and IL-22 that activate the STAT3 transcription factor; TNFα, IL-1 and IL-18 that activate NF-κB; and the IL-23 to IL-17 axis of inflammation that activates both STAT3 and NF-κB in tumor cells." (PMID 31051015, 2016). "In this study, it is observed that macrophage AEG-1 up-regulated the expression of IL-6, which may be responsible for STAT3 activation in tumor cells." (PMID 27793010, 2016). "In the context of immune escape, it has been demonstrated that activated STAT3 can be propagated from tumor cells to several immune cells, mediating a crosstalk between the two cell types, which, in turn, generates immunosuppression of both innate and adaptive immunity." (PMID 26910842, 2016). "Due to decreased proliferation and lower activation of the STAT3-cyclin D1 axis in HepG2 cells following exposure to HCMV in tumor biopsies, we assessed whether HepG2 cells infected with HCMV have a reduced oncogenic potential." (PMID 27626063, 2016). "ROS was also shown to increase p-(Y705)STAT3 in a KSHV tumor model in mice." (PMID 27458446, 2016). "In addition, vascular endothelial growth factor (VEGF) upregulates expression of Myc and Sox2 via Stat3 activation in tumor-initiating stem cells." (PMID 27589562, 2016). "This suggests that Stat3 retains a suppressive effect on mCLCA5 expression in 4T1 tumour cells." (PMID 27711075, 2016). "This implies that TKI suppression of EGFR signaling might result in a feedback activation of Stat3 signaling and thus its tumor-promoting activity as well." (PMID 27419630, 2016). "For instance, loss of Stat3 did not alter tumor onset of Neu induced tumors, and led to significantly reduced metastasis." (PMID 27589562, 2016). "Moreover, the levels of STAT3 activation in tumor tissues were impressively correlated with the levels of blood glucose of CCA patients." (PMID 26743134, 2016). "Furthermore, the JAK/STAT3 signaling pathway correlates closely with prostate CSCs and required for tumor initiation." (PMID 27521216, 2016). "These HA/CD44-activated signaling regulators (PKCε, JNK, c-Src, Nanog, Stat-3, c-Jun, Oct4, Sox2 and Twist), together with various miRNAs could be used as structure/function-related tumor markers for human cancer detection and prognosis." (PMID 27070574, 2016). "However, newer studies indicated that Stat3 exerts also tumor suppressor effects under specific conditions." (PMID 27626682, 2016). "The impaired tumour initiation capacity was found in mice injected with Stat3 knockout cells." (PMID 27553854, 2016). "Stat3 also stimulates immune responses in tumor microenvironment." (PMID 27589562, 2016). "Several studies reported elevated and tumor promoting STAT3 signaling in CRC." (PMID 27191495, 2016). "There is also evidence that the LDH-B isozyme also participates in tumor development and is regulated by oncogenic transcription factors mammalian target of rapamycin (mTOR) and signal transducer and activator of transcription 3 (STAT3)." (PMID 27242914, 2016). "RNA-seq analysis of tumor xenografts revealed that C188-9 modulated many STAT3-regulated genes involved in oncogenesis, as well as genes involved in chemoresistance and radioresistance that previously were shown to be regulated by STAT3 and STAT1." (PMID 27027445, 2016). "Given the tumor-promoting role of both NF-κB and STAT3 activations, we hypothesized that miR-K12-1 is a viral oncogene that was not identified previously." (PMID 27166260, 2016). "Stat3 ablation leads to decreased tumor cell proliferation and growth." (PMID 27460364, 2016).
tumor (continued). "In the present study, increased tumour cell expression of both ph-STAT1 and ph-STAT3 was associated with improved survival and the phenotypic characteristics of the tumour, in particular the low tumour grade and lack of tumour necrosis." (PMID 27769057, 2016). "This may be due to BPA producing its cancer-promoting effects through the STAT3 pathway, which upregulates Foxp3+ Treg cells and downregulates the Th1 inflammatory response in the tumor microenvironment." (PMID 29051427, 2016). "The anti-tumor effects of embelin could be partly attributed to its inhibition of NF-κB and STAT3 pathways." (PMID 26799669, 2016). "Furthermore, STAT3 and miR-21 are cooperative regulators of stemness, migration and tumor initiation in lung-derived BM." (PMID 26959886, 2016). "The present results suggest that STAT3 may affect disease outcome through the direct impact on tumour cells counteracting aggressive tumour features, as well as interaction with the surrounding microenvironment." (PMID 27769057, 2016). "However, in the other three cell lines we detected significant changes in the levels of cleaved Caspase3 upon STAT3 knockdown in the xenografts, which correlate with the tumor growth pattern and the STAT1 expression levels in the tumors." (PMID 27191495, 2016). "Studies demonstrated that STAT-3 inhibitors could reduce the tumor growth and induce cell apoptosis in SCCHN with activated STAT-3." (PMID 26985248, 2016). "The present study reports for the first time a negative association between ph-STAT1 and ph-STAT3 expression and tumour necrosis." (PMID 27769057, 2016). "Because of the pivotal role of STATs in tumor cell survival, proliferation, and angiogenesis, we hypothesized that STAT3 and STAT5 could be a novel therapeutic target for RCC." (PMID 26911335, 2016). "Because SC09 was an STAT3 inhibitor, we wondered whether STAT3 activation was suppressed in tumor tissues." (PMID 27705908, 2016). "Nonetheless, the tumor suppressing role of STAT3 was also reported." (PMID 27577070, 2016). "The involvement of STAT3 in energy metabolism via acetylation suggests that STAT3 may play a role in various tumour mechanisms." (PMID 28004755, 2016). "However, inhibition of STAT3 by AG490 increased the sensitivity of IL-6-treated tumor cells to doxorubicin." (PMID 27340780, 2016). "Moreover, it was shown that IL-6 promotes tumor growth by VEGF-dependent angiogenesis in particular via a STAT3 pathway." (PMID 27538520, 2016). "The persistent activation of STAT3 mediates tumour-promoting inflammation." (PMID 27756247, 2016). "We thus propose that the microenvironment created by ES cells could inhibit the tumor growth possibly through downregulating the Stat3 signal pathway." (PMID 27460364, 2016). "Moreover, interrupting STAT3 signaling in tumor cells downregulated VEGF expression and inhibited angiogenesis." (PMID 26956882, 2016). "Thus, in at least some tumor models, NK-mediated immune surveillance can be inhibited by STAT3-dependent increases in PD-L1 expression." (PMID 27148255, 2016). "Thus, the expression levels of phosphorylated and total STAT3 in these samples were analyzed by Western blot, in comparison with the tumor samples obtained from two HCC patients." (PMID 26701727, 2016). "To further demonstrate that VEGF-A/STAT3 is involved in inhibition of regorafenib-dependent tumor migration in TNBC cells, we transfected VEGF-A or STAT3 overexpression plasmid into MDA-MB-231 cells and analyzed the migration ability of MDA-MB-231 cells after regorafenib treatment." (PMID 27364975, 2016). "STAT3 activation enhances the invasive ability of tumor cells." (PMID 27602757, 2016). "It was suggested that activation of these receptors initiates NF-kB and/or STAT3 activation, which may constitute a mechanism by which the cancerous epithelial cells can manipulate inflammatory pathways to encourage tumor growth." (PMID 28536612, 2016).
tumor (continued). "Regardless of the histological types of CCA, the association of blood glucose levels and STAT3 activation was tightly bound by the fact that the levels of nuclear STAT3 in tumor tissues were significantly correlated to the levels of patient blood glucose (Spearman’s Rho = 0.896, P < 0.01)." (PMID 26743134, 2016). "This raises the question whether the STAT3 status of both tumor and immune cells is important in the general radiation response?" (PMID 27029037, 2016). "Moreover, leptin-induced STAT3 phosphorylation increased stemness in embryonic and tumor tissues, which was regulated by the feedback actions of pluripotency-associated transcription factors (i.e., NANOG, OCT4, SOX2)." (PMID 27472371, 2016). "Similarly, forced expression of another STAT3 target, Survivin, in the skin led to increased chemical-induced carcinogenesis and decreased tumor regression." (PMID 31051015, 2016). "S1PR1-STAT3 in tumor cells and myeloid cells orchestrated premetastatic niche formation, and persistent STAT3 signaling in myeloid cells could increase their proliferation and survival, as well as that of other stromal cells at future metastatic sites." (PMID 27129720, 2016). "Here, we further demonstrated EBI3 not only promoted CRC cell proliferation through the gp130/Stat3 axis, but also restrained tumor infiltrating Granzyme B+ CTLs and IFN-γ+ CTLs production to promote tumor growth in CRC by EBI3 blocking peptide in vitro and in vivo." (PMID 27247488, 2016). "However, STAT3 activation in tumor cells, as well as in other components of the immune response, can provide feedback regulation of NK cells in an indirect manner as well." (PMID 27148255, 2016). "As a recent study reported that GA suppressed lipopolysaccharide-induced nuclear factor-kB signaling, resulting in decreased production of IL-6, we wondered if GA inhibits Stat3 phosphorylation and subsequently suppresses Stat3-mediated tumor proliferation, especially in TKIR cells." (PMID 27419630, 2016). "Two characteristic STAT1/3 expression patterns with opposite growth behavior could be distinguished: cell lines with a low STAT1/high STAT3 ratio showed faster tumor growth in xenografts." (PMID 27191495, 2016). "Next, we determined whether CPA-7 inhibits STAT3 activity in the RM-9 tumor model, CPA-7 was injected in the tail vein at final concentrations of either 0.75 or 1.5 mg/kg." (PMID 27435207, 2016). "STAT1 and STAT3 are commonly considered to have opposing effects, where STAT1 have tumor suppressor properties and STAT3 may act as an oncogene." (PMID 27036022, 2016). "In addition, persistent STAT3 signaling also stimulates tumor cell migration, mediates immune evasion, and promotes angiogenesis, which contribute to oncogenesis." (PMID 26883202, 2016). "Also, commensurate with their role in regulating cytokine-dependent inflammation and immunity, the relationship between STAT1 and STAT3 and components of tumour microenvironment is unclear." (PMID 27769057, 2016). "The transcription factor STAT3 is more specifically involved in inflammatory signaling within cancer tumours and interacts with cytokines, thus by inhibiting STAT3, luteolin could also be having an anti-inflammatory effect." (PMID 27548217, 2016). "Interestingly, the tumor growth and regeneration mediated by the Wnt signaling pathway can be prevented by inhibition of gp130-Jak-STAT3 signaling." (PMID 27259262, 2016). "Given that constitutive activation of Stat3 is a frequent aberrancy in cancer cells that is supposed to directly contribute to tumorigenesis, the observed activation of Stat3 in A427 cells overexpressing the proposed tumor suppressor Lrp1b appears contradictory." (PMID 27626682, 2016). "Therefore inhibiting or demolishing the expression of active STAT3 is of great interest for both directly anti tumor treatment and tumor specific immunotherapy." (PMID 27435207, 2016).